TNF (tumor necrosis factor)
Diseases named in the same sentence as TNF in open-access papers (continued):
Sharing a sentence is not in itself a finding about the gene and the disease.
tumor (continued). "Indeed, neutralization of TNF-α by a specific monoclonal Ab significantly blocked the anti-tumor activity of Cl-IB-MECA-treated T cells." (PMID 23028986, 2012). "Ceramide accumulation induced by TNF-α or tumor development participates in the mechanism of muscle-cell atrophy, and sphingolipid metabolism is a logical target for pharmacological or nutritional interventions aiming at preserving muscle mass in pathological situations." (PMID 22257771, 2012). "Results showed that 30 days of β-carotene treatment could significantly inhibit tumour growth, enhance blood NK, IL-2, TNF-α, WBC, TP, ALB and A/G levels, and decrease blood ALT, AST and ALP activities in HCC rats." (PMID 22810193, 2012). "In culture experiments, BCG was shown to be active in stimulating tumor-necrosis-factor- (TNF-) related apoptosis in accordance with the production of cytokines including interleukin (IL)-1, IL-6, IL-8, and TNF-α, whereas the activity was tumor grade dependent." (PMID 22969822, 2012). "Serum TNF levels have been shown to be reflective of tumour load in PCa patients being low in healthy men (mean 1.1 ± 0.5 pg/mL), higher in patients with bulky locally-advanced PCa (3.9 ± 3.4 pg/mL), and highest in those with metastatic disease (lymph node and bone involvement) (6.3 ± 3.6 pg/mL)." (PMID 23326670, 2012). "NGR peptide (CNGRC) was also fused with human tumor necrosis factor alpha (TNF alpha) protein to constitute a new recombinant protein which could greatly enhance the activity of TNF alpha at very lower dose (0.3 μg) in tumor-bearing mice." (PMID 23046982, 2012). "By virtue of its dual role in tumour biology, it may appear at face value that TNF would have limited therapeutic utility against cancers because its protumour properties would nullify its antitumour effects." (PMID 23326670, 2012). "In addition to EGF, macrophages secrete multiple cytokines including TNF-α and IL-6 suggesting that macrophages in the tumor microenvironment are likely to initiate a signaling network that promotes tumor progression." (PMID 22529912, 2012). "We further tested the hypothesis that activated endothelial cells increase the growth of human tumors by incubating cultured tumor cells with conditioned culture media from either TNF-α/IFN-treated or control-treated HUVECs." (PMID 23056240, 2012). "In a de novo carcinogenesis model in which the carcinogens 7,12-dimethylbenz[α]anthracene (DMBA) and 12-O-tetradecanoyl-phorbol-13-acetate (TPA) were applied to the skin of mice, TNF−/− mice were significantly more resistant to tumour induction than wild-type animals." (PMID 23326670, 2012). "Interestingly, triptolide was shown to cooperate with tumor necrosis factor-α (TNFα) to induce apoptosis in tumor cells." (PMID 22545132, 2012). "Therefore, systemic administration of TNF was replaced in selected tumor entities successfully by regimens only employing local perfusions of extremities with TNF." (PMID 23272249, 2012). "It was suggested that downregulation of cPLA2 may attenuate TNF-α mediated apoptosis and thus may facilitate tumor progression." (PMID 23145155, 2012). "Thus, there is significant interest in understanding the molecular signaling pathways that connect TNF-α with the survival of tumor cells." (PMID 23263670, 2012). "Indeed, several reports indicate that TNF-α induces cellular transformation, proliferation, and tumour promotion." (PMID 23905066, 2012). "Tumour stromal cells, including macrophages, dendritic cells and fibroblasts, release several inflammatory cytokines, such as TNF-α, IL-1 and IL-6, which attract and recruit more inflammatory cells to the tumour microenvironment to further enhance the proliferation and survival of tumour cells." (PMID 23905066, 2012). "We first analysed the ability of TNF-α to induce apoptosis in freshly isolated tumour cells." (PMID 22719951, 2012).
tumor (continued). "Given that CD8+ T cell-derived TNFα and IFNγ can sensitize tumor stroma and mediate bystander tumor eradication, we speculate that polyfunctional CD4+ effector T cells have the same effect because these cells can produce these two cytokines simultaneously." (PMID 22400040, 2012). "Indeed, in our in situ cell death detection experiments, two out of eight STS tumours appeared to be completely resistant to TNF-α effects and three others displayed partial tumour resistance." (PMID 22719951, 2012). "First, TNF-α induces tumour initiation and promotion and enhances tumour cell proliferation." (PMID 23905066, 2012). "While TNF has been shown to promote tumour progression through its role in chronic inflammation, it is also important to note that TNF may also directly endow tumour cells with greater metastatic potential." (PMID 23326670, 2012). "TNF stimulation of tumour cells may thus directly induce aberrant PGE2 production, affecting downstream regulation of proliferation and apoptosis by PGE2." (PMID 23326670, 2012). "Depletion of CD11c+ CD207 high cells in future studies may resolve whether the influx LC cells in response to Cl-IB-MECA is sufficient for its anti-tumour effect or whether the local release of TNFα by T-cells has additional effects." (PMID 23028986, 2012). "Interestingly, Drosophila immune cells known as hemocytes have also demonstrated the ability to remove polarity-deficient cells from an epithelium through a more global extrinsic tumor suppression mechanism that is TNF/Egr-dependent." (PMID 23093933, 2012). "However, recent studies of Kym-1, HSC-3 and other tumor cell lines, suggest a unique caspase-dependent apoptosis mechanism that results from an increase in TNFα secretion and its binding to the TNFR1 receptor." (PMID 22438963, 2012). "An increased level of TNF protein in ADAM17-silenced tumors may partially result from a diminished activity of ADAM17, which prevents TNF release from tumor cells." (PMID 23251384, 2012). "It is increasingly recognized that metabolic tissue can activate the insulin growth factor signaling pathway and proinflammatory mediators, including macrophages, T cells and tumor necrosis factor-alpha, which, in turn, create a favorable microenvironment for tumor development and progression." (PMID 22911869, 2012). "In collaboration with Luciano Zardi, Laura Borsi and their team we have conducted experiments of tumor therapy in animal models by using mouse TNFα (mTNFα) covalently bound to a Fv antibody (L19) specific for the beta form of Fibronectin, selectively expressed in tumor neovasculature." (PMID 22849661, 2012). "As a result, TNF enhanced the binding of LNCaP cells to E, P, and L selectins, which may facilitate the entry of tumour cells into the bloodstream." (PMID 23326670, 2012). "Similarly, RGD peptide was also proven to be able to significantly enhance anti-tumor activity of TNF alpha at subnanogram level when combined with melphalan in tumor-bearing mice." (PMID 23046982, 2012). "TNFα was initially described as being capable of shrinking tumor size, however later studies suggested that it may stimulate tumor growth by promoting inflammation." (PMID 22947142, 2012). "Most notably, TNF-α exerts potent antitumoral effects by stimulating immune responses, including upregulation of human leukocyte antigen antigens in tumor cell surfaces, enhanced cytotoxicity stimulation of cytotoxic T cells and natural killer (NK) cells as well as epithelial healing." (PMID 22511958, 2012). "Indeed, radiological studies demonstrated the selective disappearance of tumour hypervascularized areas after treatment with TNF-α." (PMID 22719951, 2012). "However, a more complex process, in which TNF-α directly affects tumour cells, has also been postulated." (PMID 22719951, 2012).
tumor (continued). "Another possible explanation for the difference between the ADAM17 substrates is that TNF-α shedding might occur deeper within the tumour mass (where antibody penetration may be limiting) than the shedding of the EGFR ligands." (PMID 22792380, 2012). "In a mouse model of colitis-associated cancer (CAC), IKKβ was deleted in myeloid cells (leading to decreased NF-κB activity), tumor size was considerably smaller compared to controls and expression of pro-inflammatory cytokines, such as TNFα, IL-6, and IL-1, was also markedly reduced." (PMID 23284890, 2012). "Therefore, we theorize that in the Hr mutant epidermis, increased COX-2 levels in conjunction with TNFα and IL-1β create an pro-inflammatory environment that promotes tumor growth." (PMID 22761871, 2012). "The TNFα-mediated resistance to the cytotoxicity may promote tumour formation by increasing the pool of mesothelial cells with fibre-mediated genomic damage in the inflammogenic environment which evade normal cell death." (PMID 22472194, 2012). "Moreover, co-localization of nuclear staining (TO-PRO3, blue) and TUNEL (red), resulting in purple, also indicates that TNF-α induces apoptosis of tumour cells." (PMID 22719951, 2012). "Accumulation of GNP in the tumor is attested by the change in the color of the tumor; the tumor acquires a bright red/purple color (the color typical of colloidal gold and its aggregates), which coincides with the maximum of tumor-specific activity of the TNF." (PMID 22649683, 2011). "However, TNFR1−/− mice were markedly more resistant to tumor development than TNFR2−/− mice indicating that TNFR1 is the major mediator of TNF-alpha-induced tumor formation." (PMID 22162712, 2011). "Moreover, one of the consequences for TNF-á activation of tumor endothelial cells is also to recruit numerous cells through chemokines and adhesion molecules, including monocytes, neutrophils, fibroblasts and immune cells inside the tumor." (PMID 21754991, 2011). "It is now evident that tumor-associated macrophages recruited into the tumor microenvironment are producers of a wide range of proangiogenic factors, including IL-1, VEGF, IL-8, bFGF, and TNF-α." (PMID 21747968, 2011). "Constitutive TNF-α expression is detected in the tumor microenvironment of many cancers, raising the possibility that it might actually be enhancing cancer growth." (PMID 24212934, 2011). "TNF-α was identified as a cytokine that induces tumor necrosis/regression in animals." (PMID 21880146, 2011). "Significant associations were found between CCL2 & CCL5 and TNFα & IL-1β in the tumor cells in DCIS and IDC-no-relapse patients." (PMID 21486440, 2011). "In fact, TNF reportedly increased tumor metastasis to the lungs." (PMID 22190974, 2011). "Whilst TNF-alpha was first identified as a soluble factor capable of inducing tumor necrosis, various mechanisms have been described by which TNF-alpha may promote cancer growth, invasion, and metastasis." (PMID 22162712, 2011). "Indeed, many of the key soluble factors implicated in defining tumor-associated niches, such as VEGF, PlGF, SDF-1α, S100A8, S100A9, SAA3, TNF-α, and TGF-β are HSPG-binding proteins." (PMID 21698156, 2011). "Tumor accumulation of the radiolabeled SSLs was only observed in TNF-α treated animals." (PMID 21378416, 2011). "Another interesting example is the effects of macrophages on tumor development, which mainly depends on whether they secrete anti-tumor factors IL-12 and TNF-α, or pro-tumor factors IL-10, VEGF, PDGF, CXCL8, MMP-9 and TGF-β." (PMID 21760911, 2011). "Although TNF was discovered as a cytokine that could kill tumor cells, it is now clear that TNF can also contribute to tumorigenesis by mediating the proliferation, invasion and metastasis of tumor cells." (PMID 21995493, 2011).
tumor (continued). "A fusion protein comprising the 88 amino acid sequence from tumstatin 45–132 with TNFα showed inhibition of angiogenesis and tumor-cell viability in vitro, also intratumoral injection of this Tumstatin45-132-TNFα protein showed decreased blood-vessel density in xenograft F6 tumors in mice." (PMID 22267953, 2011). "IFN-γ, IFN-α and TNF-α were found to upregulate sHLA-E production by tumor cells." (PMID 21712991, 2011). "One possible mechanism could involve a CR-induced reduction of tumor necrosis factor (TNFα), which could suppress NF-κB activation in CT-2A tumor." (PMID 21479220, 2011). "This enters the gastric cells and induces TNF-alpha, an essential cytokine for tumor promotion." (PMID 21575176, 2011). "Other factor could be the TNF-α secretion in the tumor microenvironment, by MIP immunisation, which is reported to increase the permeability of tumor vessels for passage of cytotoxic drugs." (PMID 21984926, 2011). "TNF-α is a peptide hormone that affects tumor cell necrosis, inflammation, and the immune response." (PMID 21345194, 2011). "In addition, our findings demonstrate that in order to undergo EMT, the tumor cells had to be constantly stimulated by TNFα." (PMID 21486440, 2011). "This strategy, which preferentially affects tumor and not normal cells, causes a decrease in tumor cell defenses and resistance to oxidative stress inducers (such as TNF-α or ionizing radiations) and cytotoxic drugs." (PMID 24212662, 2011). "Treatment of tumour cells with LiCl strongly increased TNF-α and FasL expression." (PMID 21609428, 2011). "Indeed, silencing Bcl-xL expression significantly increased the tumor cell sensitivity to TRAIL-induced apoptosis and overexpression of Bcl-xL significantly decreased the tumor cell sensitivity to TNFα and IFN-γ-sensitized and TRAIL-induced apoptosis." (PMID 21264227, 2011). "P. acnes-treated tumor lesions were infiltrated with TNF-α and IFN-γ positive T cells." (PMID 22216160, 2011). "The cytokines, chemokines, adhesion molecules and angiogenic factors, as well as factors involved in the immune system, that we have identified in TNF-α stimulated endothelial cells may also promote tumor progression in vivo." (PMID 21754991, 2011). "To determine whether the accumulation was dependent on the volume of the tumor, we injected TNF-α plus 125I-labeled IgG or 125I-labeled SSLs into animals with a small subcutaneous tumor on one flank and a large tumor on the other flank." (PMID 21378416, 2011). "The explanation could be given, at least partly, by consideration of the extent to which receptors for TNFα and IL-1β are expressed by the tumor cells, and of which type." (PMID 21486440, 2011). "MMP production by macrophages is stimulated by TNF-α, a cytokine produced by tumour cells." (PMID 22005011, 2011). "Similarly, combination therapy additively increased the percentage of IFN-γ,TNF-α double producing CD4+ effectors in the tumor." (PMID 21559358, 2011). "Although single-agent liposomal doxorubicin alone delayed tumor growth and led to improved survival, the tumors eventually grew back, whereas the combination treatment with TNF-α and liposomal doxorubicin led to a long-term survival in 80% of the treated animals." (PMID 22036896, 2011). "Furthermore, recent findings obtained in our studies suggest that TNFα and IL-1β exert tumor-promoting activities that are connected to the ability of CCL2 and CCL5 to function as cancer-supporting factors." (PMID 21486440, 2011). "Subsequent phase I and phase II clinical trials, however, demonstrated that systemic administration of TNF was associated with severe toxicity including cytokine storm but caused little or no tumor necrosis." (PMID 24212934, 2011). "In relation to their ‘tunable’ function, mast cells in the local environment can also be detrimental for the tumours themselves, secreting immune mediators such as IL-1, IL-4, IL-5, IL-6 and TNF-α that can induce apoptosis of tumor cells and recruit inflammatory cells." (PMID 24212964, 2011).
tumor (continued). "In addition to the tumor-promoting activities of TNFα and IL-1β that have already been described, it is possible that these two cytokines also have functional interactions with CCL2 and CCL5, by that promoting disease course." (PMID 21486440, 2011). "Also, the inflammatory cells of the tumor microenvironment, consisting primarily of tumor-related macrophages, can secrete TNF-α continuously to promote tumor formation, invasion, and metastasis via activation of protein-1 (AP-1) and the NF-KB pathway." (PMID 21345194, 2011). "Treatment of the tumor cells with recombinant TNFα rapidly and transiently activated NF-κB." (PMID 21264227, 2011). "IFN-γ and TNFα may move inside the tumor through peripheral blood circulation to sensitize the tumor cells." (PMID 21264227, 2011). "In tumor environment, an increase in the expression of the inflammatory cytokines (TNF-α, IL-6, LPS) and ROS under oxidative stress is crucial for the induction of NF-κB pathway, and NF-κB can also directly activate the expression of potent EMT inducers, including Snail and ZEB factors." (PMID 21880137, 2011). "As an approach towards modelling the microenvironment in tumor tissues we here wished to address effects of TNFα, a prominent inflammatory cytokine produced by tumor infiltrating macrophages, on laminin-332 expression of Smad4-positive and Smad4-deficient tumor cells." (PMID 20307265, 2010). "However, the curative effect seems not perfect as anticipated due to its systemic cytotoxicities and resistance to tumor cells, which prevents TNFα from becoming an effective anticancer agent." (PMID 20367887, 2010). "The pattern induced by TNFα in C2C12 myotubes closely resembles that observed in the C26 tumor-bearing mice and points to ERK signaling as to another pathway by which proinflammatory cytokines may induce muscle wasting." (PMID 21048967, 2010). "Recent evidences also show that functional TLRs may play an important role in tumor progression by activating the production of interleukins, tumor-necrosis factor-alpha (TNF-α), nuclear factor-kappaBeta (NF-kappaB) and metalloproteases." (PMID 21129170, 2010). "TNFα or rather its nuclear factor-kappa B pathway acts as an early tumor suppressor." (PMID 20064207, 2010). "TNFα is one of the critical cytokines mediating tumor promoter-induced inflammation." (PMID 21297902, 2010). "This apparently paradoxical effect of TNF-α on tumour may reflect the difference in chronic synthesis and acute high-dose local administration." (PMID 20087353, 2010). "Patients with high expression of macrophages in the tumour islets have extended survival independently of tumour stage, and these macrophages demonstrate high expression of TNFα and other cytotoxic markers, suggesting they are of an anti-tumourigenic cytotoxic M1 macrophage phenotype." (PMID 20573209, 2010). "Furthermore, tumor cells co-cultivated with macrophages display a higher invasiveness through a TNFα-dependent MMP induction in macrophages." (PMID 20822533, 2010). "Therefore, TNF-α promotes tumour metastasis through its effects on tumour cells and stromal and inflammatory cells within the tumour microenvironment." (PMID 20087353, 2010). "By contrast, low dose, chronic TNF-α has angiogenic activity and promotes tumour progression." (PMID 20087353, 2010). "In this complex net work of events, in general, PGE2 serves as an immunosuppressor and inhibits the tumoricidal action of macrophages; TNF-α needs phospholipase A2 activity and free AA to bring about its anti-tumor action; while free AA and other PUFAs have direct tumoricidal action." (PMID 20932327, 2010). "Inhibition of TNF-α results in a marked reduction in tumour onset and tumour burden." (PMID 20087353, 2010). "Therefore, agents that can suppress TNFα-induced NF-κB activation, and at the same time enhance TNFα-induced cell apoptotic activation will significantly improve the anti-tumor activities of TNFα." (PMID 20367887, 2010).